MTOR (mechanistic target of rapamycin kinase)
Diseases named in the same sentence as MTOR in open-access papers (continued):
Sharing a sentence is not in itself a finding about the gene and the disease.
cancer (continued). "In priCa-1 primary cancer cells, GNE-493 treatment (250 nM, 4 h) blocked phosphorylations of S6K1 (at the Thr-389 residue) and Akt (at the Ser-473 residue), confirming Akt-mTOR cascade blockage." (PMID 35296639, 2022). "ART efficacy against cancer cells is due to ferroptosis, arrest of certain phases of the cell cycle, and inhibition of both the P13K/AKT/mTOR and MAPK pathways." (PMID 35335880, 2022). "PI3 K/AKT/mTOR, TGF-β, and Wnt/beta/catenin signaling pathways are frequently activated in human cancers." (PMID 35713434, 2022). "B7-H4 overexpression activates a variety of signaling pathways, such as the NF-κB, ERK1/2, AKT/STAT3 and PI3K/AKT/mTOR pathways, to promote epithelial-mesenchymal transition (EMT) and invasion of cancer cells." (PMID 35410218, 2022). "Blood biopsies with versus without functional ARID1A alterations also more frequently harbored alterations in ≥1 gene in many important cancer-related pathways, such as signal transduction, RAS/RAF/MAPK, PI3K/Akt/mTor, and the cell cycle." (PMID 36077815, 2022). "FC101 modulates the MAPK and mTOR pathways downstream of EGFR, both of which are vital to cancer cell proliferation, survival, and development of drug resistance in advanced cancer (e.g., TNBC)." (PMID 36428475, 2022). "In cancer cell lines, ouabain activates Src kinase and PI3K/Akt/mTOR; Src kinase mediates activation of EGFR and downstream Ras/MAPK signaling." (PMID 35150740, 2022). "Computational analysis revealed several biological processes and cancer-related pathways which are potentially regulated by 5′-tiRNA-ProTGG, including AMPK signaling, autophagy, MAPK signaling and MTOR signaling." (PMID 35625858, 2022). "In recent years, studies on the formation of EGFR heterodimers with family partners, or other RTKs, respectively to promote cancer or drug resistance through multiple pathways, including PI3K/AKT/mTOR, Ras/MEK/ERK, and JAK/STAT have been conducted." (PMID 35681787, 2022). "Glycolytic cancers upregulate GLS and move to glutamine metabolism following resistance to mTOR treatment." (PMID 35204484, 2022). "The ALKBH5-mediated m6A modification led to DDIT4-AS1 overexpression in PDAC, and DDIT-AS1 increased cancer stemness and suppressed chemosensitivity to GEM by destabilizing DDIT4 and activating the mTOR pathway." (PMID 36056355, 2022). "Among the common kinases, the mTOR, AKT1, SRC, FYN, and GNB2L1 are the kinases that are common in ALS and cancers and also identified as hub genes from the PPI network." (PMID 36590916, 2022). "Cancer cells die by autophagy with Beclin-1 accumulation, LC3-II formation, p62 degradation, and RAPTOR phosphorylation in the mTOR complex." (PMID 35280788, 2022). "mTOR inhibition suppresses the stemness of HCC cells, thereby suggesting that the β1 integrin/Akt/mTOR/SOX2 pathway mediates stiffness-induced cancer cell stemness in HCC." (PMID 35163745, 2022). "Given the promising preclinical data and mounting evidence of the efficacy of PI3K/mTOR inhibitors in other cancer types, additional studies are needed to investigate PI3K/mTOR inhibitors in cSCC." (PMID 35408839, 2022). "Despite the correlation with human cancers, the PI3K/Akt/mTOR pathway is also responsible for the pathogenesis of many other human diseases, such as osteoarthritis, stroke, asthma, and traumatic brain injury." (PMID 36072472, 2022). "Overall, PI3K isoform-specific inhibitors have demonstrated high rates of stable disease in PIK3CA-altered cancers and are better tolerated than pan-PI3K and dual PI3K/mTOR inhibitors." (PMID 35887235, 2022).
cancer (continued). "The activation of several oncogenic signaling pathways, including mTOR, BRAF, and c-Myc has been shown to increase cancer cell glycolysis and lead to lactate accumulation within the tumor microenvironment(TME)." (PMID 36573240, 2022). "The key driving forces behind cancer (CSC) stem cells, including PI3K/AKT/mTOR and JAK/STAT3, had been shown to be highly regulated in high-CSC cancers, and clinical trials are being conducted to identify small molecules that target these pathways." (PMID 35769912, 2022). "After multivariate and LASSO analyses, seven cancer-essential FRGs (ISCU, NFS1, MTOR, EIF2S1, HSPA5, AURKA, and RPL8) were used to construct the risk model." (PMID 35756689, 2022). "In CRC, BCL-3 was shown to promote cancer cell growth and survival by phosphoinositide 3-kinase (PI3K) and mammalian target of rapamycin (MTOR) mediated activation of the AKT pathway." (PMID 35468497, 2022). "Amongst an array of signaling pathways aberrantly activated in cancer Wnt, JAK/STAT, PI3k/Akt/mTOR, Notch, NF‐κB, Hedgehog, and TGF‐β/Smad pathways are crucial for the of self‐renewal, cell growth, metastasis of CSCs, and angiogenesis." (PMID 36226253, 2022). "Reactive oxygen species (ROS) can activate the Akt/mTOR and AMPK signaling systems to induce cancer." (PMID 35456005, 2022). "The cancer cell invasion index and DRG axon growth index were suppressed in the HGF + sh mTOR group compared with the HGF group." (PMID 35449152, 2022). "As is well known, the AKT/mTOR pathway is one of the important signaling pathway downstream of ALK, and it plays an important role in cell proliferation and survival in cancer." (PMID 35459209, 2022). "Torin2 is a potent inhibitor of mTOR, ATM, and ATR and has been previously shown to inhibit the growth of several different cancers." (PMID 35406510, 2022). "To better understand the potential mechanism of action of these compounds in human cancer cells, we also conducted an EGFR enzymatic assay and evaluated the PI3K/AKT/mTOR downstream signaling pathway." (PMID 36015186, 2022). "It is known that the regulation of HIF-1 is closely related to the PI3K/Akt/mTOR pathway, and it has even been shown that Akt and HIF-1 interact synergistically during the development of cancer." (PMID 35359411, 2022). "Studies have shown that the inhibition of VEGF/PI3K/mammalian targets of rapamycin (mTOR)/ERK signaling reduces angiogenesis, cancer growth, and metastasis." (PMID 35163369, 2022). "The findings demonstrated that the expression of markers of epithelial–mesenchymal transition (EMT) and cancer stem cells (CSCs) was dramatically elevated in chemoresistant EOC cells, coupled with the activation of PI3K/Akt/mTOR signaling." (PMID 36428613, 2022). "Genetic alterations of mTOR pathway-related genes, including PI3K, AKT and PTEN, facilitate tumorigenesis and are common in human cancers." (PMID 35974365, 2022). "For example, cerberin, a cardenolide isolated from the fruit kernel of Cerbera odollam, induces antiproliferation, anti-migration, apoptosis, ROS production, and DNA damage in cancer cells, accompanied by inhibiting PI3K/AKT/mTOR signaling." (PMID 36139919, 2022).
cancer (continued). "Overall, available data suggest intracellular cathepsins are active players in uncontrolled cancer cell proliferation, specifically by interfering with the pro-survival and proliferation PI3K/Akt/mTOR pathway." (PMID 36289617, 2022). "In mechanistic studies, phenformin has been shown to suppress cancer progression by inhibiting epithelial-mesenchymal transformation and the ERK, AKT, or mTOR pathway." (PMID 36006549, 2022). "Multiple signaling pathways were also involved in the pharmacological actions of magnolol against cancer, such as PI3K/Akt/mTOR signaling, MAPK signaling and NF-κB signaling." (PMID 36234977, 2022). "Although the PI3K/mTOR inhibitors PKI-587, NVP-BEZ235, and omipalisib were demonstrated to suppress NHEJ to sensitize cancer cells to radiotherapy and/or chemotherapy, ZSTK474 did not exert the same effect." (PMID 35872860, 2022). "In HCC cells, ectopic expression of the cancer stem cell marker CD90 increases sphere formation, soft agar growth, and tumorigenicity via the AMPK and mTOR pathways." (PMID 36114703, 2022). "BCAT usually promotes cancer proliferation and invasion by activating the phosphatidylinositol 3-kinase (PI3K)/protein kinase B, (PKB; Akt)/mammalian target of rapamycin (mTOR) pathway and Wnt/β-catenin signaling." (PMID 36119495, 2022). "Seven anti-HCC core targets (CASP3, EGFR, ERBB2, mTOR, MMP9, HIF1A, and PPARG) followed the pathways in cancer." (PMID 35959427, 2022). "We investigated the correlation between the expression of GSDM genes and ten famous cancer related pathways, including TSC/mTOR, RTK, RAS/MAPK, PI3K/AKT, Hormone ER, Hormone AR, EMT, DNA Damage Response, Cell Cycle and Apoptosis pathways." (PMID 35164740, 2022). "Among the various factors that can lead to the onset of cancer, one that plays an important role is the alteration of the PI3K/AKT/mTOR pathway." (PMID 36555736, 2022). "Non-flavonoid Phenolic Compounds: Curcumin decreased glucose uptake and lactate formation in cancer cell lines (H1299, MCF-7, HeLa, and PC3) via blocking the mTOR-HIF-1α interaction system and down-regulating PKM2 expression." (PMID 36339566, 2022). "Overall, this research sheds new light on the interrelationship between the IGF-1R/PI3K/mTOR and YAP/TAZ cancer-related pathways." (PMID 35284040, 2022). "Magnoflorine induces cancer cell apoptosis and autophagy by regulating PI3K/AKT/mTOR and p38 MAPK signalling." (PMID 36678509, 2022). "In this context, SSD and its compounds inhibit cancer cell proliferation through two downstream signaling pathways, viz., RAS/Raf/MAPK and PI3K/Akt/mTOR." (PMID 36139460, 2022). "Compelling evidence shows that adiponectin modulates a wide range of signaling pathways involved in the survival and proliferation of cancer cells, many of which are critical modulators of cellular metabolism, such as AMPK and mTOR." (PMID 34986886, 2022). "In the cancer cell-DRG coculture system, the cancer cell invasion index and DRG axon growth index, which were inhibited by knockdown of mTOR expression, were recovered by HGF." (PMID 35449152, 2022). "It was reported that the PI3K/Akt/mTOR signaling pathway, EMT, and cancer stem cells played important roles in tumor progression, metastasis, and chemoresistance." (PMID 35433438, 2022). "Another prominent class of PI3K inhibitors is the dual PI3K/mTOR inhibitors, which have been regarded as a highly promising drug class due to the sheer importance of the PI3K/AKT/mTOR signaling axis in cancer biology." (PMID 35406424, 2022). "The pathogenesis and progression of cancer involves aberrant regulation of signaling pathways, including MAPK, Wnt/β-catenin, PI3K/AKT/mTOR, STAT3, and NF-κB pathways." (PMID 35408483, 2022).
cancer (continued). "Specifically, the PI3K/mTOR pathway leads to cancer cell survival and migration, whereas the MAPK/ERK pathway promotes cancer cell metabolism and proliferation." (PMID 35296101, 2022). "Most of the drugs highly similar to BR were enriched with anti-cancer drugs, and their known MoAs included the inhibition of epidermal growth factor receptor, RAF, MAPK/ERK Kinase, SRC, and mTOR signaling pathways." (PMID 36304143, 2022). "This review describes that tanshinone has shown promising efficacy in various cancers through the multifaceted modulation of PI3K and mTOR targets." (PMID 36712689, 2022). "In this mini-review, we summarize the regulation of WNT/β-catenin, AKT/mTOR, matrix metalloproteinases, JAK/STAT, MAPK, and NOTCH pathways by baicalein in different cancers." (PMID 35955525, 2022). "In this context, FC101 also serves as a promising anti-cancer agent for TNBC, because it powerfully modulates the mTOR pathway." (PMID 36428475, 2022). "Mechanistically, DDIT4-AS1 recruits UPF1 to destabilize DDIT4 and activate the mTOR pathway, suggesting the crucial roles of DDIT4-AS1 in cancer progression." (PMID 36056355, 2022). "These miR-99 family members negatively regulate IGF1R or downstream protein synthesis signaling molecules, including MTOR and RPTOR in cancer cells, macrophages, and dermal cells." (PMID 35159261, 2022). "Multiple signaling pathways were also involved in the pharmacological mechanisms of magnolol against cancer, such as PI3K/Akt/mTOR signaling, MAPK signaling and NF-κB signaling." (PMID 36234977, 2022). "The PI3K/AKT/mTOR and RAF/MEK/ERK pathways are intriguing aspects of human cancer therapy and are two complex cascades containing many targets." (PMID 36539659, 2022). "Next, signaling pathways targeted by the top 20 correlated drugs were analyzed in each cancer, and we found that high PN score patients were more sensitive to drugs targeting the WNT signaling, ERK/MAPK signaling, and PI3K/MTOR signaling pathway." (PMID 35769504, 2022). "The role of mTOR in sustaining HSP90 and BRCA-1 expression level in stressed cancer cells was demonstrated in this setting by using NVB-BEZ-235, dual mTOR inhibitor that strongly downregulated both proteins." (PMID 35752616, 2022). "To address the molecular mechanism underlying AV’s effect, we first analyzed the key enzymes in major proliferation and survival pathways, commonly activated in cancer cells, PI3K/Akt/mTOR and MAP kinase pathways." (PMID 36497315, 2022). "By contrast, in vitro studies have identified alterations in MYC, mTOR, and PIK3CA, but notably rarely KRAS alterations, as potential drivers of resistance in MET-addicted cancer cells with MET-amp." (PMID 35326531, 2022). "In vitro experimental studies revealed that many phyto-colorants expressed anticancer activity through various mechanisms of targeting signaling mediators in cancer metabolism, including PI3K/Akt/mTOR, Bax/Bcl-2/caspases, and NF-kB/Nrf2." (PMID 36077338, 2022). "The CLDN6 gene acted as the oncogene in HCC and enhanced cancer cell invasion, migration, and proliferation through EGFR/AKT/mTOR signaling pathway." (PMID 35150083, 2022). "Curcumin targets multiple pathways (Wnt/β-catenin, Notch, NF-κB, PI3K/Akt/mTOR, MAPK and Hh pathways) to exert its anti-cancer effects." (PMID 35248069, 2022). "Viperin is induced in the tumor microenvironment via PI3K/AKT/mTOR/HIF-1α and IFN signaling pathways to promote cancer metabolism." (PMID 36227691, 2022). "EGFR-TKIs inhibit tumor growth by blocking the activation of EGFR in cancer cells and the downstream MAPK (RAS/RAF/MEK/ERK) and PI3K/AKT/mTOR signaling pathways." (PMID 36034789, 2022).
cancer (continued). "AKT/mTOR pathway and AMPK pathway has been proved to be related to cancer progress and cell energy metabolism." (PMID 35148777, 2022). "The mTOR and MAPK signaling pathways are necessary to promote growth and proliferation in many cancer cell types." (PMID 36506551, 2022). "LINC00152 is involved in various signaling pathways leading to cancer progression, including the ERK/MAPK, β-catenin, mTOR, and PI3K signaling pathways." (PMID 36033524, 2022). "ROS possess different functions at different stages in cancer progression and are involved in the regulation of multiple cell survival pathways, including PI3K/AKT/mTOR and MAPK/ERK mitotic signaling to drive cell proliferation." (PMID 35629355, 2022). "Mechanistically, cancer cells with reduced NOP56 are subjected to higher levels of ROS and rely on mTOR signaling to balance oxidative stress and survive." (PMID 35039048, 2022). "Thus, as one might expect, dysregulation of mTOR and its downstream cascades have been shown to play a role in cancer development and progression, with the vast mTOR signaling cascade providing a host of viable therapeutic targets to treat different cancer types." (PMID 35184380, 2022). "Lastly, the most significant Reactome signaling pathways with Benjamini–Hochberg correction and FDR < 0.001 were PIP3 activates AKT signaling, PI3K/AKT signaling in cancer, signaling by ERBB2, and MTOR signaling." (PMID 35773405, 2022). "In this review, we outline the regulation and oncogenic role of mTOR signaling, as well as recapitulate and discuss mTOR complex 1 (mTORC1) inhibition to improve the efficacy of RLT in cancer." (PMID 36612012, 2022). "Prior Western blotting experiments confirmed that FC101 simultaneously inhibits the activity of the MAPK pathway (corresponding to p-ERK reduction) and the mTOR pathway (corresponding to p-S6K and p-S6 reduction) in MAPK-driven TNBC cancer cells." (PMID 36428475, 2022). "The PI3K/Akt/mTOR pathway plays an important role in modulating the biological functions of cancer cells, and PI3K/Akt/mTOR pathway activation is tightly related with GC progression." (PMID 35209807, 2022). "Surprisingly, it is clarified that mTOR upregulation and reduced upstream AMP-activated protein kinase levels are indispensable to converting cancer cells to cancer stem-like cells mediated by Sox-2 overexpression in reprogrammed breast cancer cell lines." (PMID 36064437, 2022). "Our results are the first findings to indicate that WGM extracts induces cell death in Hep3B cancer cells and that the induction of vacuoles formation and cell death coincides with the PI3K/Akt/mTOR and MAPK signaling pathways." (PMID 36506551, 2022). "Because DEPTOR affects the signalling of mTOR and PI3K, which are key modulators of cell growth, survival, and proliferation, the relationship between DEPTOR and cancer is a promising research focus." (PMID 35078427, 2022). "The KEGG pathway analysis suggested that the effect of acupuncture was primarily related to the mTOR signaling pathway, MAPK signaling pathway, and proteoglycans in cancer." (PMID 36212128, 2022). "One of the main activators of mTOR is the PI3K/AKT axis that forms, together with mTOR, a pathway frequently hyperactivated in cancer and also involved in CDK-i resistance." (PMID 35712501, 2022). "Several PI3K/AKT/mTOR inhibitors and MAPK/ERK targeted therapies are currently under evaluation in clinical trials against a variety of human cancers, including OC." (PMID 35372029, 2022).